CCR2 (C-C motif chemokine receptor 2)
Diseases named in the same sentence as CCR2 in open-access papers (continued):
Sharing a sentence is not in itself a finding about the gene and the disease.
melanoma (continued). "The major chemokine/chemokine receptor interactions occurring in melanoma development and progression include the CXCR4/CXCR7/CXCL12, CXCR3/CXCL9,10,11, CXCR1,2/CXCL8, CCR2/CCL2, CCR4/CCL17,22, CCR5/CCL5, CCR7/CCL21 and CCR10/CCL27 axes." (PMID 37170733, 2023). "Compared to primary melanomas, MCP‐1, and its corresponding receptors CCR2 and CCR4, have been shown to be overexpressed in MBM." (PMID 37759347, 2023). "Next, astrocyte-melanoma interactions, via MCP-1/CCR2 axis activation, were explored by comparing the expression of CCR2 in FFPE sections of human PM and MBM matched samples or in cryosections of murine PM and in MBM models." (PMID 35980743, 2022). "In this study, we investigated the reciprocal role of MCP-1/CCR2 axis interactions between astrocytes (and BME) and melanoma cells in supporting MBM progression, while establishing an immunosuppressive microenvironment." (PMID 35980743, 2022). "A considerable difference is also confirmed between CCR1 and CCR2 with regard to the recruited IM subsets, with CCR1 presenting a potential therapeutic target in pulmonary metastasis from melanoma." (PMID 36241867, 2022). "CCL2 induces overexpression of the Cavα2δ1 subunit in the VGCCs of primary afferents and melanoma cells, as well as overexpression of CCL2 receptors (CCR2 and CCR4)." (PMID 34575835, 2021). "To overcome the lack of therapeutic efficacy by either blocking MCP-1 or blocking CCR2 or CCR4 with pharmacological agents, we present a CRISPR/Cas9 double K/O in melanoma cells to target the activation of an alternative compensatory pathway activated by MCP-1 involved in MBM, such as MCP-1/CCR4." (PMID 35980743, 2022). "Therefore CCR1, CCR2 and CCR5 presented as candidate targets for preventing pro-tumourigenic IM accumulation in melanoma lung metastasis." (PMID 36241867, 2022). "As well as the ligands of CCR2 being important in melanomagenesis, UV radiation has been shown to increase the secretion of CXCL8 (formerly known as IL-8), perhaps one of the most important chemokines for melanoma growth and survival." (PMID 34830780, 2021). "To assess the efficacy of CCR2 antagonist and anti-PD-1 combination treatment in models beyond bladder cancer as well as in metastatic disease, we examined the efficacy of this combination in the treatment of B16F10 melanoma pulmonary metastases." (PMID 33247183, 2020). "A group has investigated the use of a dominant negative CCL2 construct lacking 2-8 amino acids at its N-terminus (7ND) targeting CCR2 in a melanoma mouse model." (PMID 21943176, 2011). "The presence of CCR2 enabled these inducible nonclassical monocytes to infiltrate both intra- and extravascular metastatic sites of melanoma, lung, breast, and colon cancer in murine models, and they reversed the increased susceptibility of Nod2–/– mutant mice to cancer metastasis." (PMID 39545417, 2024). "Hence, with the intention of blocking the interaction of cancer cells expressing CCR2 (and CCR4) with MCP-1 secreted in MBM (from astrocytes and other sources of cells in the brain, including tumor cells), we knocked out CCR2 and CCR4 genes in melanoma cells, using the CRISPR/Cas9 system." (PMID 35980743, 2022). "We found that B16–BL6/Zs green melanoma cells secrete CCL2 spontaneously; thus, the tumor mass could directly affect the excitability of nociceptive neurons in our animals, and might induce the upregulation of CCL2 receptors (CCR2 and CCR4), as has been previously suggested." (PMID 34575835, 2021). "However, a recent study using a B16 mouse melanoma model demonstrated that neither Ccr2 nor Ccr5 deficiency affect tumor infiltration of adoptively transferred CD8+ T cells, despite the fact that the tumor expresses high levels of CCL2 and CCL5 (ligands for CCR2 and CCR5, respectively)." (PMID 30483271, 2018). "Thus, CCR2, but not CCR6, drives activated γδT17 cell migration to inflammatory sites during B16 melanoma and EAE." (PMID 28580944, 2017).
Stroke (58 papers, 2010 to 2026). Sudden impairment of blood flow to a part of the brain due to occlusion or rupture of an artery to the brain. "Stroke severity is associated with the level of CCR2 expression and the number of infiltrated monocytes." (PMID 37452512, 2023). "CCL2 mediates monocyte migration from the bone marrow into the bloodstream by binding to CCR2, whose expression is associated with stroke severity." (PMID 37452512, 2023). "C-C chemokine receptor 2 (CCR2) + Mo/MΦ have been found to spread through the brain tissue in the early phase of stroke and have been implicated in both early stage inflammation and later functional recovery." (PMID 35250546, 2022). "Meanwhile, deficienc in CCL2 and CCR2 greatly reduce the recruitment of macrophages after stroke, the size of the cerebral infarction area, and the degree of BBB disruption after ischemia-reperfusion injury." (PMID 34276530, 2021). "It was shown that selective deficiency of CCR2 in monocytes leads to a reduced infiltration after experimental stroke." (PMID 33058417, 2020). "In an additional study, circulating CCR2+ monocytes were depleted with an anti‐CCR2 monoclonal antibody during the first week after stroke, which caused a reduced recovery of motor function as late as 11 weeks post‐ischemia." (PMID 33058417, 2020). "A possible explanation is that in conditions of high blood pressure, patients carrying risk allele(s) suffer from cerebrovascular accident more than others due to direct or indirect effects of CCR2/CCR5 on blood–brain barrier and blood vessel of brain." (PMID 22769019, 2012). "MDM depletion in the ischemic brain of CCR2 knockout (KO) mice results in a smaller infarct size 3 days after stroke but is associated with greater injuries, higher mortality, and reduced functional recovery 14 and 28 days after stroke." (PMID 37452512, 2023). "Up-regulation of MCP-1 has been shown to underlie hypoxic preconditioning-induced stroke tolerance in mice; whereas, activation of CCR2 is involved in the neuroprotective effects exerted by both ischemic preconditioning and post-conditioning in mice subjected to global cerebral ischemia." (PMID 25972779, 2015). "Additionally, CCL2 and its receptor CCR2 have been implicated in post-stroke leukocyte trafficking." (PMID 32872405, 2020). "Blocking myeloid cell recruitment using anti-CCR2 antibody and CCR2 gene knockout mice impaired long-term spontaneous behavioral recovery after stroke via reducing anti-inflammatory macrophages and angiogenesis." (PMID 40667795, 2025). "This heterogeneity is consistent with previous literature on CCR2 expression and outcomes after stroke as retention of CCR2 expression on monocyte precursors is important for post-stroke recovery while CCR2 on mature monocytes does not have the same effect." (PMID 38070624, 2024). "In a model of ischemic stroke, CX3CR1 KO mice have larger damaged areas than WT and CCR2 KO mice 48 h after stroke." (PMID 37452512, 2023). "Acutely following stroke, CCR2 KO mice exhibited larger infarct volume, cerebral oedema, worse neurological function as well as increased blood brain barrier permeability." (PMID 37957163, 2023). "In experimental stroke, blocking CCR2 to inhibit monocyte recruitment protects against brain edema but impairs long‐term recovery." (PMID 37452512, 2023). "In the experimental stroke model, inhibition of CCR2+, which was highly expressed by a subset of monocytes, showed a protective effect on cerebral ischemia damage by producing anti‐inflammatory cytokines, attenuating the infarct volume and brain edema." (PMID 35588444, 2022). "Animal studies and clinical trials have shown that CCL2/CCR2 mediate the pathological process of ischemic stroke, and a higher CCL2 level in serum is associated with a higher risk of any form of stroke." (PMID 35408846, 2022).
Stroke (continued). "The majority of monocytes initially recruited to the brain after stroke are Ly-6Chi (CCR2+) cells, which differentiate primarily into M1 tissue macrophages in the stroked hemisphere and promote inflammation." (PMID 35795678, 2022). "We used a combination of immunostaining, flow cytometry, and CCR2 reporter mice to examine the temporal and cellular origin of gliosis in the thalamus after stroke." (PMID 34131204, 2021). "This indicates that infiltration of peripheral immune cells through the CCL2/CCR2 axis contributes to the neuroinflammation present after experimentally induced stroke." (PMID 33918875, 2021). "The signaling pathway for MCP-1 is connected with CC chemokine receptor 2 (CCR2), which also plays an important regulatory role during stroke." (PMID 34276530, 2021). "In this study, we compared blood TNF, TNFR1, TNFR2, CCL2, and CCR2 levels in stroke patients and healthy controls and investigated the association of TNFR1, TNFR2, CCL2, and CCR2 levels to stroke severity, infarct size, and functional outcome at 90 days." (PMID 33918875, 2021). "We found that the expression levels of some chemokines and cytokine receptors, such as CSF1R, CSF1, CCL3, CD4, and CCR2, were significantly different in ki20227-treated stroke mice compared to vehicle-treated stroke mice." (PMID 33177990, 2020). "The same result can be repeated using CD11b-DTR mice or targeting of CCR2 in bone marrow-derived cells suggesting monocyte-derived macrophages were essential for establishing integrity after stroke." (PMID 32596397, 2020). "C–C motif chemokine ligand 2 (CCL2) is associated with neurological repair after stroke and delivery of various cells into the brain via CCL2/CCR2 (CCL2 receptor) interaction." (PMID 33096826, 2020). "This migration of inflammatory cells is promoted by CCL2/CCR2 interactions, which induces translocation of CCR2-expressing inflammatory cells into infarct areas already experiencing increased CCL2 expression following a stroke." (PMID 33096826, 2020). "In the acute phase of stroke, bone marrow-derived peripheral monocytes are recruited into the brain through a CCR2 (chemokine receptor 2)-dependent mechanism and their numbers peak at day 3 to day 4 after stroke." (PMID 33042113, 2020). "A recent report indicated that CCL2 is associated with neurological repair after stroke and delivery of various cells into the brain via CCL2/CCR2 interaction." (PMID 33096826, 2020). "In a recent study using CCR2 knockout mice, after MCAO and reperfusion, the infarct size was less in CCR2 KO mice with lower mortality when compared to WT control when measured 3 days after stroke." (PMID 31291966, 2019). "Nonetheless, CCR2 KO mice had high mortality and neurological deficit from 5 to 28 days after stroke." (PMID 31291966, 2019). "In a focal ischemic model, it has been reported that many CCR2+ Mo/MΦ that had invaded after the stroke later transdifferentiated to CX3CR1+ Mo/MΦ20." (PMID 29844029, 2018). "MCP-1/CCR2 signaling is involved in numerous neuroinflammatory diseases, such as multiple sclerosis, stroke, and Alzheimer’s disease." (PMID 29976212, 2018). "While CCR2+ Mo/MΦ predominated during the first 3–5 days after stroke, CX3CR1GFP/+ Mo/MΦ number strikingly increased at 14 and 28 days." (PMID 27814740, 2016). "Studies in experimental stroke (middle cerebral artery occlusion model (MCAo)) confirmed involvement of chemokine CCL2 and its receptors CCR2 in stroke development." (PMID 24324296, 2013). "In the hypertensive group, CCR2 rs1799864, CCR5 rs1799987 and CCL11 rs4795895 were nominally associated with increased risk of stroke." (PMID 22769019, 2012). "Previous studies have shown that genetic ablation of MCP-1 or its receptor CCR2 resulted in reduced cerebral injury closely related with an attenuated accumulation of monocytes and macrophages after stroke." (PMID 21625615, 2011).
Stroke (continued). "Although different chemokines and receptors, like monocyte chemotactic protein-1 (MCP-1 or CCL2) and CCR2, are involved in immune cell activation and chemotaxis after stroke, an approach aiming at multiple targets remains to be proven." (PMID 21625615, 2011). "While our study found very low expression of CCR2 mRNA and protein in normal or stroked WT brain, consistent with previous endothelial transcriptome atlases, we found that loss of Slc4a4 results in an upregulation of endothelial CCR2, contributing to exacerbated BBB damage after stroke." (PMID 38709635, 2024). "Ly6C-high monocytes may therefore play a protective role in SAH, as in other stroke types in which the knockdown of CCR2 improves the neurological function of mice." (PMID 37978532, 2023). "In addition, we evaluated post-stroke changes in monocyte subsets and neutrophils, along with their surface expression of CCR2, TNFR1, and TNFR2." (PMID 33918875, 2021). "Therefore, activation of the CCL2/CCR2 pathway can recruit inflammatory cells and release pro-inflammatory factors, which are detrimental to the stroke prognosis." (PMID 34276530, 2021). "In addition, as a marker of monocytes, increased CCR2 mRNA expression is indicative of monocyte infiltration after stroke." (PMID 33177990, 2020). "However, deficiency of CCR2 or its ligand CCL2, and thus, reduced monocyte infiltration after stroke has also been associated with smaller infarct sizes, a reduction in pro‐inflammatory cytokine expression, and thus, a better functional outcome." (PMID 33058417, 2020). "CCR2+Ly6Chi monocytes are the main population of infiltrating monocytes in mouse studies of stroke." (PMID 33058417, 2020). "We observed increased stem cell engraftment by CCL2-overexpressing hUC-MSCs as compared with naïve hUC-MSCs and found that elevated CCR2 levels in the peri-infarction area during acute phase of stroke promoted the migration of CCL2-overexpressing hUC-MSCs into the brain." (PMID 33096826, 2020). "However, at 14 and 28 days after stroke, CCR2+ cells are mainly found in the lesion core, which is surrounded by CX3CR1+ monocytes/macrophages as shown by the transfer of CX3CR1GFP/+CCR2RFP/+ bone marrow into wild‐type mice." (PMID 33058417, 2020). "However, blocking monocyte recruitment using anti-CCR2 antibody at 1 week post-stroke eliminates long-term behavioral recovery with significant decrease in anti-inflammatory gene expression in an MCAO mice model with 30 min occlusion." (PMID 31291966, 2019). "Mice that had bone fracture 6-hours before pMCAO also had more bone marrow-derived macrophages (40.4±9.78% of DAPI labeled nuclei, CCR2+) in the peri-infarct regions compared to stroke-only mice (24.4±5.15%, p = 0.001) and bone fracture 24 hours before pMCAO mice (24.0±5.57%, p = 0.001)." (PMID 27089041, 2016). "Furthermore, it has been shown that CCL2 activates microglia by triggering the release of IL-1β and TNF-α as well as by up-regulating their CCR2 expression level in a mouse model of stroke." (PMID 27930721, 2016). "Indeed, it is believed that the CCR2/CCL2 axis is a potent pathway for «Ly6Chi» inflammatory monocytes recruitment into the CNS in models of stroke, Alzheimer’s disease and EAE." (PMID 27930721, 2016). "Sustained presence of CCR2+ monocyte-derived inflammatory MPs have been shown to play an important role in neurodegenerative diseases such as models of multiple sclerosis, experimental autoimmune encephalitis and stroke." (PMID 24142887, 2013). "Furthermore, CCR2-null mice were protective against cerebral inflammation following ischemia, suggesting that CCR2 is a contributing factor for stroke-induced injury." (PMID 21159187, 2010). "In this study, upregulation of chemokine receptors CCR5 and CCR2—both linked to inflammatory cell migration—was observed, which might be consistent with findings that CCR5 antagonists can improve neurological outcomes post-stroke." (PMID 40896336, 2025).
Stroke (continued). "Furthermore, we found CCR2 but not CCL2 to correlate with time to blood sample, SSS, and mRS, suggesting that CCR2 may be a potential biomarker for stroke severity and functional outcome." (PMID 33918875, 2021). "Thus, targeting the inhibition of the CCL2 expression or its receptor CCR2 could improve the prognosis of stroke." (PMID 34276530, 2021). "The Ly6Chigh murine equivalent of the human classical monocytes and neutrophils enters ischemic lesions in the brain in a CCR2-dependent manner, and the ablation of CCR2 decreases infarct size, although CCR2 monocytes have also been shown to be neuroprotective after stroke." (PMID 33918875, 2021). "Therefore, we speculated that increased CCR2 levels in the brain following stroke might promote translocation of CCL2-overexpressing hUC-MSCs to the brain parenchyma." (PMID 33096826, 2020). "Additionally, the proportion of CCR2-RFP+ CD11b+ cells remains unchanged by experimental stroke meaning it is unlikely that TipDC and moDC, which are both derived from recruited monocytes under conditions of inflammation contribute to increased CD11b+ cells in the spleen after stroke." (PMID 29872438, 2018). "Indeed, depletion of circulating CCR2 monocytes impairs long-term spontaneous behavioral recovery after stroke, while Ly6Clo monocyte deficiency does not affect functional recovery and severity of injury after hypoxia/ischemia in mice." (PMID 27814740, 2016). "Whereas CCR1, CCR2 and CCR5 expression was found to be unchanged, a reduced gene transcription of the microglial-associated chemokine receptor CX3CR1 was observed after stroke in TREM2-KO mice compared to littermate control mice (12 h: to 79% ±6.7; 7 d: to 50% ±4.6, p≤0.05, n = 5/6 each)." (PMID 23301011, 2013). "The chemokine receptors CCR2, CCR5, CXCR2, CXCR3, CXCR4 and CX3CR1 are constitutively expressed in the human brain, and their expression is enhanced under pathological conditions, including stroke and neurodegenerative diseases like HIV-associated dementia (HAD) and Alzheimer’s disease (AD)." (PMID 23210607, 2012). "After stroke, CCL2/CCR2 induces microglial recruitment, increases leukocyte infiltration and the expression of inflammatory mediators, further aggravates damage to the BBB, and leads to brain edema and neuronal death." (PMID 40289984, 2025). "After a stroke, MCP-1 is upregulated in reactive astrocytes and microglia in the cortex and striatum, and the MCP-1 receptor, CCR2, is expressed in new neuroblasts." (PMID 37242489, 2023). "The exacerbated stroke outcomes in diabetic mice were accompanied by the upregulated expression of inflammatory factors (including IL-1β, TNF-α, IL-6, CCR2, and MCP-1) in the ischemic brain." (PMID 35784349, 2022). "In this study, laminin was increased 7 days after the occlusion in all the stroke groups (wildtype, and in CX3CR1 and in CCR2 knockouts)." (PMID 35743229, 2022). "Neutrophils and monocytes infiltrate the brain parenchyma after stroke onset, with monocytes being recruited preferentially through the chemokine (C-C motif) ligand 2/C-C chemokine receptor type 2 (CCL2/CCR2) axis." (PMID 33918875, 2021). "Both bone marrow-derived macrophages (CCR2+) and microglia (CX3CR1+) increased in the peri-infarct regions of mice subjected to bone fracture before pMCAO compared to stroke-only mice." (PMID 27089041, 2016). "Further studies have shown that a subpopulation of bone marrow-derived monocytes/macrophages, recruited via CCR2 and acting through TGF-β1, maintains the integrity of the neurovascular unit in murine stroke models." (PMID 25972779, 2015). "Monocyte depletion, chemokine (C-C motif) receptor 2 (CCR2) knockout, and bone marrow chimeric approach in murine stroke models demonstrated that CCR2 in bone marrow-derived cells alters injury and hemorrhagic transformation." (PMID 25426016, 2014).